HNRNPA1 (heterogeneous nuclear ribonucleoprotein A1)
Diseases named in the same sentence as HNRNPA1 in open-access papers (continued):
Sharing a sentence is not in itself a finding about the gene and the disease.
pancreatic ductal adenocarcinoma (2 papers, 2022 to 2025). An infiltrating adenocarcinoma that arises from the epithelial cells of the pancreas. "For instance, hnRNPA1 could recognize the specific DNA conformation of KRAS, a G4 structure, and form an EGF-KRAS-ILK-hnRNPA1 regulatory loop to maintain the invasive activity of pancreatic ductal adenocarcinoma (PDAC) cells." (PMID 35879279, 2022).
proteinopathies (2 papers, 2020 to 2024). "Interestingly, nuclear loss of hnRNPD (DL, AB) was found to associate with increasing cytoplasmic pTDP-43 as well as with decreasing nuclear hnRNPA1, A0 and C to suggest the involvement of this understudied subfamily in the pathogenesis of TDP-43 proteinopathies." (PMID 39670112, 2024).
acute leukemia (1 paper, 2016). A clonal (malignant) hematopoietic disorder with an acute onset, affecting the bone marrow and the peripheral blood. "In support for a role of hnRNPA1 in lymphoid neoplasms, aberrant expression of hnRNPA1 was described in acute leukemia." (PMID 27303665, 2016).
adenoma (1 paper, 2021). A neoplasm arising from the epithelium. "Interestingly, a study in mice showed that during lung oncogenesis initially expression of hnRNPA1 and SRSF1, which act antagonistically in splice site selection to regulate AS, rose together in adenomas, but hnRNPA1 increased much further in tumors reaching 6-fold higher protein levels." (PMID 34065983, 2021).
amyloid (1 paper, 2020). "MBNL sequestration by CUG expansion RNAs in DM1 results in enhanced APP exon 7 skipping, while HNRNPA1 knockdown leads to expression of full-length APP (+exon 7), which has been suggested to lead to increases in Aβ peptide secretion and amyloid plaques." (PMID 32086392, 2020).
aortic stenosis (1 paper, 2021). Aortic valve stenosis is a aortic valve disease caused by the incomplete opening of the aortic valve. "Increased hnRNPA1 expression in heart muscle of patients experiencing aortic stenosis, ischemic cardiomyopathy, or dilated cardiomyopathy is noted, although its release in circulation was not examined." (PMID 34479416, 2021).
autoimmune neurological diseases (1 paper, 2021). "Heterogeneous nuclear ribonucleoprotein A1 (hnRNPA1) is a major component in the formation of SGs and is discussed as a factor in the pathogenesis of autoimmune mediated CNS neurological diseases and as a link between SGs and autoimmune neurological diseases." (PMID 34248597, 2021).
brain tumour (1 paper, 2023). "Alterations in RBP expression levels and function have been associated with neurological disorders (e.g. HNRNPA1, MATR3, TIA1, and TARDBP and brain tumour development (e.g. Musashi1, SERBP1, PTB and HuR." (PMID 37294214, 2023).
cardiomyopathy (1 paper, 2025). A disease of the heart muscle or myocardium proper. "Prominently downregulated proteins (TUBGCP2, NPR2, MT-ATP6, SLC25A11, and so on) were enriched in cytoskeletal dynamics and cardiomyopathy pathways, while upregulated proteins (ATP6V0D2, HNRNPA1, TPM1, and so on) associated with oxidative stress responses and neurodegenerative disorders (AD and PD)." (PMID 40662159, 2025).
Colorectal Tumors (1 paper, 2018). "Next, we examined protein expression levels of PTBP1, hnRNPA1, and SRSF3 in clinical colorectal tumor samples." (PMID 30279379, 2018).
essential tremor (1 paper, 2014). A relatively common disorder characterized by a fairly specific pattern of tremors which are most prominent in the upper extremities and neck, inducing titubations of the head. "We sequenced the exons coding the NES domains of five RNA-binding proteins (TARDBP, hnRNPA2B1, hnRNPA1, TAF15 and EWSR1) that have been previously implicated in neurodegeneration in a series of 257 essential tremor (ET) cases and 376 healthy controls." (PMID 25375143, 2014).
gastric adenocarcinoma (1 paper, 2016). "Instead, SRSF7 in gastric adenocarcinoma was higher in intestinal-type, which has a higher survival rate than diffuse-type, and HNRNPA1 levels in CRC were higher in well-differentiated, without nodal involvement, or low-stage groups." (PMID 27282379, 2016). "None of the SRSF 5–7 and HNRNPA1 proteins showed significant relationships with unfavorable histopathologic or aneuploidy status in gastric adenocarcinoma or CR-adenocarcinoma." (PMID 27282379, 2016). "In the semiquantitative immunoblot analysis, HNRNPA1 and SRSF7 levels were significantly higher in GC than in gastric normal mucosa, and SRSF7 levels were higher in intestinal-type compared with diffuse-type of gastric adenocarcinoma." (PMID 27282379, 2016).
heart failure (1 paper, 2025). Inability of the heart to pump blood at an adequate rate to meet tissue metabolic requirements. "The cardiac‐specific RBP Hnrnpa1, which was identified by single‐cell omics, triggered daughter CM formation by promoting CM dedifferentiation and cell cycle activity in a post‐transcriptional manner, indicating that Hnrnpa1 is a promising therapeutic target for heart failure after MI." (PMID 39559922, 2025).
hypospadias (1 paper, 2020). Hypospadias is the displacement of the urethral meatus on the ventrum of the penis. "FGFR2, whose mutations were associated with hypospadias, might be coregulated by SFPQ and HNRNPA1." (PMID 32316190, 2020).
Influenza infection (1 paper, 2022). "Based on our findings that NP and hnRNPA1 interact and co-localize in the same cellular compartments, we investigated if Influenza infection influenced hnRNPA1 protein expression in a dose-dependent manner." (PMID 35215793, 2022).
lentivirus infection (1 paper, 2021). Virus diseases caused by the Lentivirus genus. "HnRNPA1-flag fusion protein was overexpressed using a lentivirus infection system and then pulled down with the application of anti-flag magnetic beads (left)." (PMID 34222256, 2021).
lymphoid neoplasm (1 paper, 2016). A neoplasm composed of a lymphocytic cell population which is usually malignant (clonal) by molecular genetic and/or immunophenotypic analysis. "Activation of ERK1/2 would then lead to activation, amongst others, of MYC and hnRNPA1, two proteins previously shown to contribute to tumor formation in lymphoid neoplasms." (PMID 27303665, 2016).
male infertility (1 paper, 2020). The inability of the male to effect fertilization of an ovum after a specified period of unprotected intercourse. "EGFR, the signalling dysfunction of which was associated with human male infertility, might be coregulated by FXR1, FXR2, and HNRNPA1 (all of these three bind EGFR from CLIP experiments), G3BP2, G3BP1, FMR1, and SRSF7." (PMID 32316190, 2020). "CFTR, mutations of which are associated with male infertility, might be coregulated by FXR1, HNRNPA1, MATR3, PABPC1, G3BP2, FMR1, and SRSF7." (PMID 32316190, 2020).
mood disorder (1 paper, 2019). A cognitive disorder a disturbance in which the person's mood is hypothesized to be the main underlying feature. "Many genes, e.g. FOS, DUSP1 and HNRNPA1, were up-regulated in more than one condition, suggesting potential molecular links between sleep deprivation and mood disorders." (PMID 34691834, 2019).
myocardial infarction (1 paper, 2025). Gross necrosis of the myocardium, as a result of interruption of the blood supply to the area, as in coronary thrombosis. "With the use of α‐MHC‐H2B‐mCh/CAG‐eGFP‐anillin transgenic mice, Hnrnpa1 overexpression promoted CM DACCA, thereby triggering daughter CM formation and enhancing cardiac repair after myocardial infarction (MI)." (PMID 39559922, 2025).
myotonic dystrophy type 1 (1 paper, 2021). Steinert disease, also known as myotonic dystrophy type 1, is a muscle disease characterized by myotonia and by multiorgan damage that combines various degrees of muscle weakness, arrhythmia and/or cardiac conduction disorders, cataract, endocrine damage, sleep disorders and baldness. "Both are involved in fetal splicing activities, and Hnrnpa1 upregulation is known to be involved in an imbalance of RNA-processing factors causing myotonic dystrophy type 1 (DM1)." (PMID 34669013, 2021).
oral cancer (1 paper, 2024). "In this circumstance, hnRNPA1 controls the expressions of target genes linked to the G2/M stage, further promotes the growth of oral cancer cells, and activates telomerase to lengthen telomeres, resulting in the initiation and development of malignant tumors." (PMID 38785973, 2024).
pancreatic adenocarcinoma (1 paper, 2024). "Moreover, analysis from TCGA revealed that HNRNPA1 is obviously overexpressed in LIHC, and other gastrointestinal tumors including COAD, CHOL, ESCA, pancreatic adenocarcinoma (PAAD), and rectum adenocarcinoma (READ)." (PMID 39247822, 2024).
sarcopenia (1 paper, 2015). Progressive decline in muscle mass due to aging which results in decreased functional capacity of muscles. "Key findings potentially related to sarcopenia at multiple levels of muscle metabolism in hereditary IBMs like IBMPFD and GNE myopathy as well as the HNRNPA1-associated multisystem proteinopathy presenting as IBM will be highlighted." (PMID 25729363, 2015).
SARS-CoV infection (1 paper, 2023). "In the context of SARS-CoV infection, DEAD-box helicase 1 (DDX1) RBP has been shown to facilitate template read-through and thus replication of genomic viral RNA, while heterogeneous nuclear ribonucleoprotein A1 (hnRNPA1) might regulate viral RNA synthesis." (PMID 36814457, 2023).
Senile plaques (1 paper, 2019). Senile plaques are extracellular deposits of amyloid in the gray matter of the brain. "Another important gene, HNRNPA1 the human orthologue for sqd-1, is involved in alternative splicing of APP genes that could be targeted for reducing senile plaque formation." (PMID 31291334, 2019).
skin cancer (1 paper, 2017). "But the report about mechanisms of hnRNPA1 regulating MDM2 expression in skin cancer cells is poorly." (PMID 28035066, 2017).
small cell lung carcinoma (1 paper, 2021). Small cell lung cancer (SCLC) is a highly aggressive malignant neoplasm, accounting for 10-15% of lung cancer cases, characterized byrapid growth, and early metastasis. "hnRNPA1 regulates alternative splicing of interferon regulatory factor 3 and affects immunomodulatory functions in human non–small cell lung cancer cells." (PMID 33573689, 2021).
testis tumor (1 paper, 2020). "FGFR3, which has a role in testis tumor development might be coregulated by a different set, SFPQ, FXR2, and HNRNPA1, and all three bind it based on POSTAR2." (PMID 32316190, 2020).
thymic lymphoma (1 paper, 2017). "In conclusion, FIR haplodeficiency switches PKM1 to PKM2 in thymic lymphoma, possibly by affecting hnRNPA1 expression." (PMID 28978087, 2017). "Notably, FIR haplodeficiency promoted the splicing of PKM1 to PKM2 in mice thymic lymphoma without circulating tumor cells/bone marrow invasion revealed by flow cytometry analysis through potentially inhibiting hnRNPA1 expression." (PMID 28978087, 2017).
thyroid cancer (1 paper, 2019). "Combination of hnRNPA1 knockdown and JQ1 also decreased Survivin levels in thyroid cancer cells." (PMID 31480735, 2019).
vacuolar myopathy (1 paper, 2024). "Mutations of the hnRNPA1 gene subtype are reported to cause a genetic form of IBM, with a chronic vacuolar myopathy with ultrastructural tubulofilamentous inclusions lacking inflammation and hnRNPA1 aggregates co-localized with p62 in small aggregates as well." (PMID 39012547, 2024).
ventricular septal defect (1 paper, 2018). The presence of a defect (opening) in the septum that separates the two ventricles of the heart. "Histological analysis revealed normal anatomy in both wild-type littermate controls and Hnrnpa1+/ct heterozygotes, whereas all 3 Hnrnpa1ct/ct homozygotes displayed ventricular septal defect (VSD) and persistent truncus arteriosus (PTA), which was caused by complete failure of OFT septation." (PMID 29367466, 2018).
Wilms’ tumour (1 paper, 2024). "This spliceosomal vulnerability likely extends to other components of the spliceosomal machinery such as HNRNPA1, RBM39 and SNRPD3, as well as other cancers such as Wilms’ tumour, where our transcriptomic analyses revealed MYCN regulation of spliceosome regulators including SNRPD1 and WDR77." (PMID 39313128, 2024).
cancer (124 papers, 2010 to 2025). A tumor composed of atypical neoplastic, often pleomorphic cells that invade other tissues. "Loss of this single PTM greatly diminishes HNRNPA1’s ability to support cancer cell proliferation, migration, invasion, and tumorigenicity." (PMID 41275207, 2025). "Heterogeneous nuclear ribonucleoprotein A1 (hnRNPA1) plays a critical role in RNA metabolism, including alternative splicing, which is linked to cancer progression." (PMID 39834948, 2024). "We aimed to explore the cancer-associated function of whole sEV-miRNAs that were loaded by hnRNPA1 integrally." (PMID 34222256, 2021). "Loss of hnRNPA1, hnRNPC1, or hnRNPD induces cell death and proliferation arrest in cancer models and these proteins were decreased in response to peptide treatment." (PMID 33859938, 2021). "Roles of HNRNPA1 are beginning to emerge in cancers; however, mechanisms causing deregulation of HNRNPA1 function remain elusive." (PMID 34961772, 2021). "As an oncogene, heterogeneous nuclear ribonucleoprotein A1 (HNRNPA1) was associated with cancer development and was supposed to be a promising therapeutic target in cancer." (PMID 33457194, 2020). "It is, thus, not surprising that deregulation—typically overexpression—of hnRNPA1 has been linked to a variety of diseases including cancer." (PMID 32417965, 2020). "An aberrant expression of heterogeneous nuclear ribonucleoprotein A1 (hnRNPA1) has been found in various types of cancer and is associated with splicing regulation to promote apoptosis resistance and survival." (PMID 33339170, 2020). "Moderate to strong hnRNPA1 immunostaining was also linked with higher numbers of deletions present in a cancer." (PMID 32417965, 2020). "HNRNPA1 regulated AS of the androgen receptor (AR) and gave rise to a splice variant AR-V7, which conferred drug resistance toward enzalutamide in cancer cells." (PMID 31355251, 2019). "Consistent with the previous observation that patients with higher HN1 expression have worse survival prognosis, higher HNRNPA1 expression was also associated with lower survival rates in multiple cancer types." (PMID 31257225, 2019). "Dysregulation of hnRNPA1 has been associated with various diseases, including cancer." (PMID 37897508, 2024). "The hnRNPA1 protein can mediate miR-196a packaging into cancer-associated fibroblast-derived EVs." (PMID 35655924, 2022). "Paclitaxel and cisplatin promote miR-522 secretion from cancer-associated fibroblasts by activating USP7/hnRNPA1 axis, leading to arachidonate lipoxygenase 15 suppression and decreased lipid-ROS accumulation in cancer cells and ultimately promote acquired chemoresistance in gastric cancer." (PMID 33967786, 2021). "While the effect of HNRNPA1 on miR-21 transcription is possibly indirect, an HNRNPA1 guided network may hold the potential to decipher transcriptional deregulation of miRNAs implicated in cancers." (PMID 34961772, 2021). "Moreover, USP7 deubiquitinates and stabilizes heterogeneous nuclear ribonucleoprotein A1 (hnRNPA1) to enhance the secretion of cancer-associated fibroblast (CAF)-derived exosomes, which transfer miR-522 to enhance the chemoresistance of GC cells." (PMID 34512150, 2021). "However, subset analyses revealed that hnRNPA1 overexpression was associated with 9 of 11 deletions in ERG-negative cancers (p < 0.05) and with 6 of 11 deletions in ERG-positive cancers (p < 0.05)." (PMID 32417965, 2020). "In addition, the up-regulation of hnRNPA1 and alternative splicing effect on many types of oncogenic genes had been tightly associated with the proliferation or motility of cancer cells." (PMID 28035066, 2017). "In addition, Hematopoietic- and neurologic-expressed sequence 1 (HN1) is associated with the senescence phenotype of cancer cells, and low expression of hnRNPA1 in cancer cells contributes to the prolongation of the 3'UTR on HN1, which regulates cancer cell senescence." (PMID 40384875, 2025).
cancer (continued). "Importantly, the shikonin-caused dysfunction of hnRNPA1 may further provide a sound pharmacological basis for the potential application of shikonin in cancer immunotherapeutics, for example, in DC-based cancer vaccines." (PMID 28674499, 2017). "Pan-cancer analysis revealed that HNRNPA1 was highly expressed in a variety of gastrointestinal tumors including HCC and associated with shorter DFS and OS in HCC patients." (PMID 39247822, 2024). "Previous results confirmed that hnRNPA1 affects the growth and survival of cancer cells and becomes active proteins in cancer cells." (PMID 39834948, 2024). "HNRNPA1 has been extensively studied in cancer, where it influences cell proliferation, invasiveness, metabolism, and stress adaptation by regulating the expression and translation of key genes associated with tumorigenesis and cancer progression." (PMID 39717265, 2024). "As an SF, hnRNPA1 can influence apoptotic gene expressions in cancer cells via regulating alternative splicing, mRNA stability, translation, and protein degradation." (PMID 38785973, 2024). "The silencing of hnRNPA1 resulted in reduced proliferation and increased apoptosis in Hep G2 cells, confirming its critical function in cancer cell dynamics." (PMID 39834948, 2024). "hnRNPA1 can facilitate the switch from PKM1 to PKM2 in cancer cells, which accelerates glycolysis and cancer initiation." (PMID 38785973, 2024). "It is suggested that hnRNPA1 plays different roles in cancer cells even within the same organ, which is dependent on mRNA splicing." (PMID 38268030, 2024). "Although SRSF1 and hnRNPA1 are both frequently upregulated in cancer, they have opposite functions in AS events." (PMID 37988165, 2023). "Silencing of hnRNPA1 induces senescence in normal and cancer cells and inhibits cancer-related phenotypes such as colony formation and cell migration." (PMID 37296881, 2023). "It is upregulated in cancers and exceptionally frequent in oncogenes including hnRNPA2B1 and hnRNPA1." (PMID 37296881, 2023). "After proving specific interaction between hnRNPA1 and FEN1 rG4, the correlations between the expression of FEN1 and hnRNPA1 in different types of cancer tissues were analyzed by the GEPIA database." (PMID 36829835, 2023). "Several studies have also shown that the hnRNPA1 gene is a target of activated CMYC in various cancers." (PMID 37296881, 2023). "Of these, HSPA8, HSPA9, PKM, HNRNPA1, NPM1, ANXA2 are already reported to be associated with LN metastasis in GBC or other cancers." (PMID 37142981, 2023). "HNRNPA1 has important cancer-promoting effects in many tumors, but its function in PTC is rarely reported." (PMID 35022405, 2022). "Mechanically, hnRNPA1, a classical RBP, is involved in regulating the splicing and maturation of various key cancer genes, in which hnRNPA1 arginine methylation was found to play a prominent role." (PMID 35879279, 2022). "Increased HNRNPA1 expression is found in multiple cancer types, and positively correlates with BECN1 expression, and is proposed to mediate cancer development." (PMID 35585060, 2022). "A cancer study reported depletion of hnRNPA1 and hnRNPA2 resulted in a concomitant decrease of PKM2 mRNA in Hela and 293 cells." (PMID 35153787, 2022). "In summary, there have been many studies showing that HNRNPA1 is closely related to a variety of malignant tumors, but so far, there has been little research on the correlation between HNRNPA1 expression and PTC progression." (PMID 35022405, 2022). "Currently, eight hnRNPs members (hnRNPA1, hnRNPA2B1, hnRNPC, hnRNPD, hnRNPF, hnRNPK, hnRNPR, and hnRNPU) seem to be more relevant to cancer development, according to reported literature." (PMID 35875075, 2022). "HnRNPA1 was also intimately involved in promoting intercellular communication between mesenchymal cancer cells and blood vessel endothelium." (PMID 35879279, 2022).